RNU6-275P (RNA, U6 small nuclear 275, pseudogene)
Gene: Small nuclear RNA gene on chromosome 12 (8,484,746 to 8,484,852, forward strand). Ensembl gene ENSG00000201780.
Homologues: Orthologues: chimpanzee U6 (99% identical), dog U6 (64% identical), mouse Gm54812 (61% identical). Paralogues in human: RNU6-727P (86% identical), RNU6-1062P (84% identical), RNU6-338P (84% identical), RNU6-43P (84% identical), RNU6-1091P (83% identical), RNU6-24P (83% identical), RNU6-379P (83% identical), RNU6-797P (83% identical), RNU6-1056P (82% identical), RNU6-1060P (82% identical), RNU6-115P (82% identical), RNU6-1243P (82% identical), and 1284 more.